NPY (neuropeptide Y)
Diseases named in the same sentence as NPY in open-access papers (continued):
Sharing a sentence is not in itself a finding about the gene and the disease.
Anxiety (continued). "The high co-expression with Crhr1 and stimulatory nature of the glucagon receptor suggest that like NPY, glucagon is a signal for a negative energy balance that affects in parallel food intake and anxiety." (PMID 30210279, 2018). "Because NPY itself has been shown to affect anxiety, we considered the possibility that a change in NPY release may accompany a decrease in GAD67 in NPY+ cells." (PMID 30024942, 2018). "Many genes, such as ADORA2A, NPY, DRD2, GABRB3, has shown relation with panic disorder in few studies, with supporting evidence of each gene having relation with panic disorder or, in part, anxiety related function." (PMID 31435520, 2018). "Combined with the anxiety behavior observed, this suggests that GABA release from NPY+ interneurons may play a role in innate behaviors at adolescent ages." (PMID 30024942, 2018). "We previously demonstrated increased anxiety behavior and impaired learning ability and recognition in the memory in the EMD mice that could be related to the high NPY expression now demonstrated in the cerebral cortex." (PMID 28143489, 2017). "Serum NPY levels were increased by treatment with escitalopram and venlafaxine in the patients with depression, but not in the patients with anxiety." (PMID 28824541, 2017). "Obviously, according to the results of this study, mood disorders (anxiety and depression) do not appear simultaneously following ND-induced decrease of hippocampal NPY content." (PMID 28582442, 2017). "Intranasal infusion of NPY after exposure to traumatic stress in the single prolonged stress (SPS) protocol, rodent model of PTSD, averted the elevation of anxiety, depressive-like behavior and hyperarousal observed in vehicle treated animals a week or more afterwards." (PMID 28469551, 2017). "Exposure of WT mice to EE reduced anxiety and decreased central glucocorticoid receptor expression, effects which were absent in NPY KO mice." (PMID 27305846, 2016). "These experiments were designed to discover whether stressful decision-making influences gene expression related to neuroplasticity (BDNF, TrKB, GluR1, GluR4) and anxiety (NPS, NPY) in a brain region known to participate in decision-making." (PMID 24782729, 2014). "In fact, the reduced NPY transmission may be related to increased CRF and noradrenergic transmission determining anxiety and depression behaviors." (PMID 23986909, 2013). "We performed analyses of NPY and Y2R content and function to evaluate the effects of deletion of Y2R from GABA neurons on the function of extended amygdala brain regions critical for anxiety, depression, alcohol drinking, and fear behaviors studied here." (PMID 24399943, 2013). "NPY levels are lower in the CeA of alcohol-preferring (P) rats compared to non-P (NP) rats, and NPY infusion in the CeA attenuates the anxiety-like and alcohol drinking behaviors of P rats." (PMID 23584117, 2012). "Importantly, growing evidence suggests that neuropeptide Y (NPY), which is activated during states of hunger, increases appetite and alleviates anxiety symptoms, as well as promoting the extinction of fear responses, which may have adaptive significance." (PMID 40944223, 2025). "In addition, since NPY is closely related to depression and anxiety, it may lead to conclusions that EMF emitted from mobile phones triggers anxiety in infant rats." (PMID 40636869, 2025). "Furthermore, independently of its origins, no studies have addressed how endogenously released NPY modulates LCNE activity to regulate anxiety levels." (PMID 40700482, 2025). "In a mouse model of anxiety and depression behavior induced by social isolation with chronic unpredictable stress, RES treatment significantly increased levels of the neurotransmitters dopamine and serotonin in the prefrontal cortex, along with increased expression of NPY in the brain." (PMID 39275174, 2024).
Anxiety (continued). "This can indicate that NPY may not be an effective therapy for preventing anxiety-like behavior and social anxiety in females or that perhaps a higher dose is required." (PMID 34566592, 2021). "This indicates that NPY exerts anxiolytic-like effects when administered into the DH, DLS, CeA and BLA, but not when administered into the MeA, and suggests that partly distinct neural circuitries mediate the effects of NPY on the expression of social fear and on anxiety-like behavior." (PMID 33918123, 2021). "Contrary to our hypothesis, improvement of anxiety scores did not lead to significant changes in circulating NPY levels which was the main focus of this study." (PMID 33192409, 2020). "Therefore, the NPY-KO zebrafish exhibited severe anxiety responses to acute stress, but the social interaction in NPY-KO showed small difference with wild type unlike non-stress condition." (PMID 32246073, 2020). "Unlike for the NPY, the serum αMSH levels did not correlate with alterations in anxiety levels." (PMID 30863280, 2019). "Interestingly, the stronger (negative) effect of TE on serum NPY was followed by the stronger anxiety-like effect of TE compared to ND in the combined groups." (PMID 30863280, 2019). "The fact that the most significant (positive) correlation between NPY/MC4R ratio and the anxiety unequivocally confirms that this new parameter could be, due to its highest significance, a useful tool for estimation of anxiety level in behavioral investigations." (PMID 30863280, 2019). "We hypothesize that a low protein diet (LPD) during pregnancy and lactation would induce anxiety- and depression-like behaviors in adult offspring, and that these behaviors would be reflected in the regulatory interactions between the IEG and NPY systems in hypothalamus and amygdala." (PMID 28894112, 2017). "In the first probe trial (removal of the box 48 h after the last training session), the time spent in the target quadrant, a parameter not affected by hypolocomotion or anxiety, was significantly shortened in EE-housed NPY KO mice (36.4 ± 10.6 s vs. 75.8 ± 11.2 s), indicating a memory deficit." (PMID 27305846, 2016). "Unlike WT mice, NPY KO mice hardly ever use the running wheel but extensively interact with the hay tunnel, which may be related to their anxiety-prone phenotype." (PMID 27305846, 2016). "Decreases in CREB phosphorylation and downstream cAMP-inducible genes, including NPY in the central and medial, but not the basolateral, nuclei of the AMG, have been associated with a predisposition to both anxiety-like and excessive alcohol-drinking behaviors in alcohol-preferring rats." (PMID 27766083, 2016). "Implicating NPY in depression-like phenotypes, administration of the NPY Y1 receptor agonist NPY (Leu31, Pro34) had anxiolytic and antidepressant effects on cholecystokinin-4 (CCK-4)-induced anxiety-like behavior in the SIT and depression-like behavior in the FST." (PMID 25762938, 2015). "Neuropeptide Y (NPY) neurons within the ARC were identified over three decades ago as potent stimulators of food intake and adiposity, and later on as important regulators of the hypothalamic-pituitary-adrenal (HPA) axis, sympathetic activity, and anxiety related behaviors." (PMID 25324716, 2014). "The involvement of NPY in addiction was mainly studied with regard to alcohol dependence, with alcohol-preferring rats having lower basal levels of NPY in the CeA that correlate with greater levels of anxiety-like behavior compared with alcohol non-preferring rats." (PMID 23761766, 2013). "Thus, an extensive regulatory network in the amygdala, comprising NPY, CRF, GABA, CREB, the cAMP/PKA signaling pathway, and possibly CART peptides, may influence stress-induced anxiety and drug intake." (PMID 23584814, 2008).
Anxiety (continued). "In addition, to determine whether the reduced CREB level contributes to alcohol-induced anxiety of in cHAP mice, we may infuse activators for CREB’s upstream protein kinase PKA, or Neuropeptide Y, one of the CREB-targeted genes, into the amygdala, hippocampus or prefrontal cortex in future study." (PMID 33767622, 2021). "Besides, the monoamine hypothesis proposes that the serotonin (5-HT), norepinephrine (NE), dopamine (DA), and neuropeptide Y (NPY) pathways play a crucial role in the pathophysiology of depression and anxiety and may aggravate depression and anxiety and sensorimotor deficits." (PMID 34135004, 2021). "However, improvement of anxiety scores did not lead to significant changes in NPY." (PMID 33192409, 2020). "Finally, NPY is a component of a neuropeptide system that is highly expressed in limbic areas of the brain, where it regulates fear- and anxiety-related behavior, while mice lacking NPY or one of its receptors (Y2) exhibit heightened generalization to auditory cues." (PMID 30697153, 2018). "Interestingly, systemic administration of an Y2R antagonist was shown to reverse increases in anxiety-like behavior after alcohol withdrawal, again implying that NPY signaling may regulate negative reinforcement." (PMID 25278825, 2014). "Although GHSRs are co-expressed on >90% of NPY/AgRP neurons in the ARC, our discovery demonstrates a specific role for GHSRs in the OB, independent from AgRP neurons in foraging and anxiety-like behavior but not food consumption." (PMID 39236785, 2024). "Notably, NPY could play a significant role in stress and anxiety independent of GABA." (PMID 29377906, 2018). "Microinjection of NPY attenuated GTN-induced allodynia and anxiety without affecting photophobia." (PMID 37231359, 2023).
depression (145 papers, 2006 to 2026). "NPY had significant associations with various subjective measures including perceived stress and depression levels." (PMID 37226227, 2023). "NPY was associated with schizophrenic disorders, depressive disorders, mood disorders, and alcohol-related disorders." (PMID 37252132, 2023). "The results revealed that during the period of ADW, when the degree of alcohol dependence was low, NPY rs16147:T>C CC homozygotes showed a lower degree of depression compared with those who carried the NPY rs16147:T>C T allele." (PMID 36245887, 2022). "A different murine model reported depression-like behavior associated with the decreased expression of NPY in the hypothalamus and hippocampus, while also inducing changes in the microbiome and brain metabolome in mice on a high-fat diet." (PMID 36004833, 2022). "supported NPY protective role in depression by detection of decreased plasma levels of NPY IgG autoantibodies in patients with depression while their increased affinities were associated with lower body mass index (BMI) and reduced appetite." (PMID 33953692, 2021). "Although low-NPY has been associated with depression, the hyperconnectivity within the salience network observed here has not been found in depression." (PMID 34867217, 2021). "It is suggested that the increase in central levels of NPY mitigate the threshold of response to stress and depression, causing a phenotype resistant to stress in animal models that present mutations in the gene that expresses DPP-IV." (PMID 34836194, 2021). "In humans it was found that genetic variations with low-expression NPY genotypes display a maladaptive responsiveness to stress that predispose to major depression and anxiety disorders." (PMID 33192409, 2020). "The level of plasma NPY is significantly increased in patients with depression, and the NPY gene can be used as a risk gene for severe depression." (PMID 33123166, 2020). "Despite these clinical findings, pre-clinical rodent models exhibiting behaviors associated with depression point towards decreased NPY in the PFC." (PMID 33192369, 2020). "The development of PTSD and comorbid depression typically is associated with stress-induced deficiency of neuropeptide Y (NPY)." (PMID 32932645, 2020). "Preclinical studies using rodent models are helping to investigate the potential of NPY to modulate behaviors associated with depression." (PMID 33192369, 2020). "Dysregulation of these neuropeptides is associated with depression, and reduced plasma levels of both NPY and CRH have been found in suicidal individuals." (PMID 31220174, 2019). "Conversely, studies suggesting that depression causes low BP have indicated that overexpressed neuropeptide Y in a patient with low BP is likely to mediate depression." (PMID 29490622, 2018). "Considering the increased prevalence of depression with age, the observation that cell loss of the NPY-positive cells in the dentate gyrus is enhanced in the depressed FSL animals as they age compared to the FRL line confirm their use as a depression model." (PMID 28824541, 2017). "The NPY system has been implicated in depression via its role in modulating stress response, mood, and affective behaviors." (PMID 25762938, 2015). "Depression has been associated with sympathetic nervous system activation and release of neuropeptides (epinephrine, neuropeptide Y), which has a suppressive effect on NK cell activity by reducing levels of perforin and granzyme B." (PMID 25663421, 2015). "Neuropeptides such as neuropeptide Y, neurokinin/substrate P and galanin have also been associated with the pathology of the more severe and debilitating form of depression called major depressive disorder (MDD)." (PMID 26854172, 2015). "Local administration of NPY into the hippocampus causes resilience against experimental models of chronic mild stress-induced depression and posttraumatic stress disorder." (PMID 25414650, 2014).
depression (continued). "A decrease in neocortical NPY has been reported for Alzheimer's disease, schizophrenia, bipolar disorder, and depression, potentially contributing to associated cognitive deficits." (PMID 24616688, 2014). "The results of this study showed that the polymorphism locus rs16139 of NPY gene was highly correlated with depression." (PMID 23468908, 2013). "In conclusion, our results provided important information for understanding the relationship between SNPs of NPY and the susceptibility to depression." (PMID 23468908, 2013). "The SNP (NPY rs16147:T>C) might be one candidate biomarker for screening individuals with a higher risk of developing depression in ADW." (PMID 36245887, 2022). "For example, people with low levels of NPY in the brain have a higher risk of depression." (PMID 36245887, 2022). "Here, we explored whether the NPY rs16147:T>C has an association with depression in individuals with alcohol dependence during the period of alcohol dependence withdrawal." (PMID 36245887, 2022). "NPY rs16147:T>C might be correlated with susceptibility for depression in males during alcohol dependence withdrawal." (PMID 36245887, 2022). "In addition, depression had led to lower NPY and T levels in the peripheral blood and caused endocrine disorders and immune disorders." (PMID 35432561, 2022). "This variation in the NPY gene increases susceptibility to stress and may contribute to the symptoms of depression." (PMID 33192369, 2020). "One study found NPY was significantly lower in victims of suicide when compared to accidental-death control subjects suggesting that NPY deficits in this region may be linked with emotional regulation and depression." (PMID 33192369, 2020). "The pre-clinical work demonstrates support for the hypothesis that NPY plays a role in regulating a specific subset of behaviors associated with depression, and further pre-clinical and clinical studies are needed to fully examine this hypothesis." (PMID 33192369, 2020). "Abnormal alterations of neuropeptide Y may explain the association between abnormal BP and depression." (PMID 32665058, 2020). "NPY has been implicated in human diseases, particularly psychiatric disorders such as depression." (PMID 32246073, 2020). "In depression, reductions in NPY levels are associated with a preproNPY SNP." (PMID 28824541, 2017). "In addition, decreased NPY concentrations are associated with conditions such as schizophrenia, depression, bipolar disorder, and Alzheimer's disease." (PMID 24616688, 2014). "Importantly, these preclinical data are relevant to findings in humans; deficiencies within the central NPY system have been demonstrated in patients with major depression." (PMID 25206349, 2014). "In Michigan, several scientists have found that persons with low levels of NPY in their brain may be at higher risk of suffering from depression." (PMID 23468908, 2013). "Therefore, the gene polymorphism loci rs16139 of NPY was closely related to the onset of depression, although its role in the pathogenesis of MDD requires further study." (PMID 23468908, 2013). "However, in NPY-deficient mice, sitagliptin showed reduced efficacy, suggesting that NPY plays an important role in mediating the effects of sitagliptin on social fear and comorbid depression." (PMID 40490517, 2025). "Moreover, some evidence showed the association of NPY with human depression." (PMID 37252132, 2023). "Furthermore, knockout of Y2 and Y4 receptors unmasks the ability of a single LPS injection to cause a delayed and prolonged increase in depression-like behavior, which indicates that NPY signaling conveys resilience to some of the adverse effects of immune stress on the brain." (PMID 29213271, 2017).